TLR4 (toll like receptor 4)
Diseases named in the same sentence as TLR4 in open-access papers (continued):
Sharing a sentence is not in itself a finding about the gene and the disease.
tuberculosis (continued). "Taken together, our results suggest that genetic polymorphisms of rs10759932 and rs2737190 in TLR4 gene may play a role in susceptibility to tuberculosis in the Chinese population." (PMID 27339100, 2016). "Moreover, HIV patients with the rs4986790-G (TLR4) allele are less likely to develop tuberculosis." (PMID 37606452, 2023). "Another mRNA vaccine contains four full-length tuberculosis antigens fused with a synthetic TLR4 agonist." (PMID 38255961, 2024). "In our previous study, we also found an association between the rs4986790-G (TLR4) allele and increased CD4 T-cell count in the group coinfected with HIV and tuberculosis." (PMID 39339847, 2024). "In a previous study, we found an association of the rs4986790 (TLR4) and rs5743810 (TLR6) polymorphisms with the risk of developing tuberculosis." (PMID 39339847, 2024). "TLR4 expression was significantly increased in patients with tuberculosis, HIV, and tuberculosis–HIV coinfection compared to the control group." (PMID 39339847, 2024). "Our study revealed certain associations between TLR4 and TLR6 polymorphisms and HIV–tuberculosis coinfection." (PMID 37606452, 2023). "Previously, we analyzed the association of SNPs in TLR2 and TLR4 genes in samples of HIV patients and HIV–tuberculosis patients in Eastern Europe and Central Asia." (PMID 37606452, 2023). "Mycobacterial components are known TLR2 and TLR4 agonists, and MyD88 dependent signaling is necessary to prevent lethality in response to infection to tuberculosis." (PMID 35921962, 2022). "DMPC-containing SE was found to stimulate the production of antigen-specific antibodies against the tuberculosis antigen ID97 in a mouse model via a TLR4-dependent process." (PMID 36559051, 2022). "The vaccine contains an adjuvant formulation CIA09, composed of DOTAP-based cationic liposomes and the TLR4 agonist dLOS, which enhances antibody and cell-mediated immune responses to tuberculosis protein antigens and inactivated JEV vaccine." (PMID 33804176, 2021). "The results show that the frequency of two SNPs in TLR4 was significantly higher in controls than in tuberculosis patients." (PMID 32411792, 2020). "TLR2 and TLR4 play a central role in the immune response against tuberculosis by secreting proinflammatory cytokines and activating other molecular mechanisms, such as autophagy, which can limit intracellular bacterial growth." (PMID 26347897, 2015). "In this study, we evaluated the gene and cell surface expression of TLR2 and TLR4 in pulmonary tuberculosis patients during anti-tuberculosis treatment." (PMID 24558401, 2014). "The combination of two SNPs in TLR4 (C→T) (rs1399431) and TNF-α (C→T) (rs7791836) predicted tuberculosis risk with 71% accuracy in blacks (P = 0.02)." (PMID 20196868, 2010). "The severity of tuberculosis tends to be negatively correlated with TLR4 expression level." (PMID 40502714, 2025). "Anti-tuberculosis drugs activated the TLR4–NF-κB–MyD88 pathway to induce liver injury, and high-dose Lc intervention inhibited the activation of NF-κB and MyD88 proteins, thus reducing oxidative stress and inflammatory response, as well as alleviating liver injury." (PMID 37298396, 2023). "In addition, TLR4 plays an active role in the induction of anti-tuberculosis immune response and participates in the killing and clearance of MTB by inducing macrophage apoptosis and downregulating the intensity of the immune response in TB patients." (PMID 37112768, 2023). "Moreover, miR-23a-3p was shown to inhibit monocyte function and phagocytosis by targeting IRF1/SP1 followed by the TLR4/TNF-α/TGF-β1/IL-10 signaling pathway in patients with active tuberculosis." (PMID 34608568, 2021). "Furthermore, investigating the TLR4-mediated response will provide insight for the development of effective control measures against tuberculosis." (PMID 32403973, 2020).
tuberculosis (continued). "Since TLR4 plays a dual role in HIV-1 infection and anti-bacterial function, rs4986790 SNP, which is associated with structural and functional alteration of TLR4, showed a relationship with the susceptibility of HIV infection and bacterial-related phenotype, including tuberculosis." (PMID 33396586, 2020). "The TLR4/CD14 complex is responsible for cytokine production via NF-κB, and the SNP CD14–159 in the promoter region has been associated with susceptibility to tuberculosis, and was shown to influence the production of IFN-γ." (PMID 28850598, 2017). "Although the role of TLR4 in host defense against tuberculosis is controversial, studies have reported that innate recognition by TLR4 may play a protective role in tuberculosis." (PMID 27711141, 2016). "This study explores the immunogenicity and tuberculosis (TB) vaccine potential of antigens (Ags) combined with Toll-like receptor 4 (TLR4) adjuvants and a stimulator of interferon genes (STING) agonist." (PMID 40414893, 2025). "Overall our data suggest that VapC12 ribonuclease toxin-mediated differential expression of M. tuberculosis proteins help in the timely resolution of TLR4-mediated inflammation which is critical for disease persistence in TB." (PMID 38515752, 2024). "In this paper, we evaluated the protective effect of Lactobacillus casei Zhang on anti-tuberculosis drug-induced liver injury in mice and explored whether Lactobacillus casei plays a protective role by regulating the gut microflora and TLR4–NF-κB–MyD88 pathway." (PMID 37298396, 2023). "Association of TLR2 polymorphism with TB has been reported in human, and in the case of Cattle, SNPs in TLR2 and TLR4 genes have been associated with susceptibility to paratuberculosis infection." (PMID 27284220, 2016). "TLR4 gene expression was significantly higher in pulmonary tuberculosis patients (TB) at the different time points of treatment (M1, p = 0.01; M2, p = 0.01; M3, p = 0.04) than in controls (C)." (PMID 24558401, 2014). "Our objective was to evaluate the mRNA and cell surface expression of TLR2 and TLR4; inducible nitric oxide synthase (iNOS) expression; and cytokine Th1, Th2 and Th17 profiles in pulmonary tuberculosis patients at different time points of anti-tuberculosis treatment." (PMID 24558401, 2014). "The median level of the CD4+ cell count in the rs4986790-AA (TLR4) genotype carriers was 1.13/2.23 times lower than in the rs4986790-AG/GG (TLR4) genotype carriers in HIV patients and HIV–tuberculosis coinfected patients, respectively." (PMID 37606452, 2023). "The table summarizes the mean percentages of inflammatory cells expressing TLR1, TLR2, TLR4, TLR7, and TLR9 in LNs from patients with AOSD, tuberculosis (Tb) lymphadenitis, T cell lymphoma, histiocytic necrotizing lymphadenitis (HNL), and reactive LNs." (PMID 35715478, 2022). "As an example, the tuberculosis vaccine candidate M72/AS01E utilizes monophosphoryl lipid A (MPLA), a TLR-4 agonist based on lipopolysaccharide (LPS), to elicit CMI." (PMID 32246076, 2020). "Our study evaluated the mRNA and cell surface expression of TLR2 and TLR4; iNOS expression; and the production and expression of IL-12, IFN-γ, TNF-α, IL-17, IL-10 and TGF-β in pulmonary tuberculosis patients during anti-tuberculosis treatment." (PMID 24558401, 2014). "Lipopolysaccharide is recognized by TLR4 and CD14, and both are upregulated in melioidosis (P = 0.0016 and 1.5 × 10–6, respectively); however, TLR4 and CD14 are also upregulated in tuberculosis (P = 1.5 × 10–6 and 9.4 × 10–4)." (PMID 23383015, 2013). "Another secreted tuberculosis protein, the adhesin heparin-binding hemagglutinin (HBHA), was found to bind TLR4, induce maturation, and activate proinflammatory cytokine secretion in dendritic cells." (PMID 22529866, 2012). "Among the TLR family, TLR2, TLR4, and TLR9 and their adaptor molecule MyD88 play the most prominent roles in the initiation of the immune response against tuberculosis." (PMID 21603213, 2011).
tuberculosis (continued). "Notably, TLR4 plays a crucial role in M. tuberculosis infection and TLR4 agonist have been developed as vaccine adjuvant candidate for TB to increase the efficacy of the existing vaccine; therefore, the vaccine models were subjected to molecular docking analysis with TLR4 in the normal mode." (PMID 39624097, 2024). "TLR4 is expressed on both cytoplasmic and endosome membranes and signals through TRIF- and MYD88-dependent pathways, thereby facilitating immunosurveillance against tuberculosis." (PMID 37813638, 2023). "The aim of our current studies is to characterize and test a prophylactic tuberculosis vaccine comprised of ID93, a polyprotein fusion antigen, and a liposomal formulation [including a synthetic TLR4 agonist (glucopyranosyl lipid adjuvant, GLA) and QS-21] in a preclinical mouse model of TB disease." (PMID 33705411, 2021). "We conclude that the level of TLR2 (but not TLR4) changes with tuberculosis infection state but not with tuberculosis disease severity." (PMID 29104936, 2017). "TLR4 and CD14 are upregulated in both melioidosis and tuberculosis." (PMID 23383015, 2013). "In support of this hypothesis, the TLRs are upregulated as a group in both melioidosis (TLR1, TLR2, TLR4, TLR5, TLR6, TLR8 and TLR10) and tuberculosis (TLR2, TLR4, TLR5, TLR6, TLR7, TLR8)." (PMID 23383015, 2013). "Summarily, the chimeric vaccine candidate (designated TB-MEVA−1) comprised 683 amino acid residues, which included 27 M. tuberculosis predicted epitopes, the incorporated immune potentiators (TLR4 agonist, TAT, and PADRE), and diverse linkers." (PMID 40004053, 2025). "According to our findings, patients with the rs4986790-G (TLR4) allele had higher concentrations of CD4+ lymphocytes compared to patients without the rs4986790-G (TLR4) allele in both the entire sample of HIV patients and in groups with/without tuberculosis coinfection." (PMID 37606452, 2023). "Others study reported increased TLR2/TLR4 mRNA gene expression in latent tuberculosis infection (LTBI) than in non infected, and increased in active TB than LTBI or healthy individuals." (PMID 35638072, 2022). "In this regard, a directly proportional expression between CD64, TLR2, and TLR4 has been described in monocytes differentiated into macrophages from peripheral blood and neutrophils from tuberculosis patients, but not in vitro macrophages differentiated to a pro-inflammatory profile." (PMID 36077408, 2022). "In another study, also in an Ethiopian cohort of HIV co-infected TB patients, 7 genes (FCGR1A, RAB24, TLR1, TLR4, MMP9, NLRC4, and IL1B) accurately discriminated between active tuberculosis disease and latent infection." (PMID 33692804, 2021). "TLR4, similar to some other TLR family members, is a critical molecule in the anti-TB immune response, through its ability to recognize M. tuberculosis and its components to trigger further innate immune responses." (PMID 29233104, 2017). "Finally, to determine if TLR4 engagement by the DMPC-containing SE adjuvant contributes to its ability to augment the adaptive immune response, we immunized WT and TLR4−/− C57BL/6J mice with ID97, a protein tuberculosis antigen, adjuvanted with squalene SE or squalene MF59-like emulsion." (PMID 36559051, 2022). "In a recent study, an increased expression of TLR-1, TLR-2, TLR-4 and TLR-6 has been reported at the mRNA level in peripheral blood mononuclear cells, but not in broncho-alveolar lavage cells from patients with tuberculosis compared to healthy controls." (PMID 20718957, 2010). "In pulmonary leucocytes obtained from patients with tuberculosis, NOD2 mRNA expression correlated with TLR2 (p = 0.02) and TLR4 (p = 0.01) but not with TLR6 mRNA expression (p = 0.17)." (PMID 17705850, 2007).
liver disease (75 papers, 2010 to 2026). "In a rodent model of steatotic liver disease, they found up-regulation of hepatic glutaminase type 1 and TLR4, which was associated with the buildup of hepatic ammonia." (PMID 40053595, 2025). "Limitations of the studies: it will be important to demonstrate the steatohepatitis exacerbating effects of fEVs in a mouse model of liver diseases at its early stage, which can be possibly blocked in nmMLCK‐ or TLR4‐deficient mice." (PMID 36708245, 2023). "High levels of this bacteria can also activate the slow inflammatory response in the liver through the TLR4 signaling pathway, causing liver disease." (PMID 35992168, 2022). "During conditions of impaired intestinal barrier function, TLR4 activation mediates gastrointestinal-associated liver disorders." (PMID 33656663, 2021). "TLR4's key function in liver diseases was further substantiated when associations between single nucleotide polymorphisms (SNPs) of the TLR4 gene in humans and risks of specific diseases, including cirrhosis, were reported." (PMID 30034633, 2018). "It has been proposed that fatty acids, particularly saturated fatty acids may act as endogeneous ligands of Toll-like receptors 4 (TLR4), thereby promoting inflammation and dylipidemia-associated liver disease." (PMID 40980810, 2025). "To manage effective treatment options for gastrointestinal-associated liver diseases by developing new drugs, we elucidated the cross-talk between TLR4-induced inflammation and potential therapeutic medicines that facilitate the interaction between the gut and the liver." (PMID 33656663, 2021). "Importantly, the role of TLR4 in fibrogenesis has also been identified and confirmed by specific SNP alleles in TLR4 being associated with a delayed progression of fibrosis in liver disease and conferring an overall protective effect." (PMID 32555351, 2020). "However, the role of Wnt2b in TLR4-associated hepatic inflammation and fibrosis-related liver diseases is still unclear." (PMID 28638086, 2017). "This differential role of TLR4 might be due to interaction with the pre-existing liver disease (ABCB4 deficiency)." (PMID 27391331, 2016). "Background/Objectives: Liver inflammatory diseases are a major global health burden and are often exacerbated by inflammation driven by lipopolysaccharides (LPS) through toll-like receptor 4 signaling." (PMID 40283890, 2025). "In liver diseases, signaling pathways such as TLR4 and NF-κB activate endogenous cellular inflammatory vesicles, releasing pro-inflammatory cytokines like IL-1β, IL-6, and TNF-α." (PMID 39936090, 2025). "Overall, these findings showed that macrophage CAR activation attenuated endotoxin‐induced liver injury and hepatic inflammation through the TLR4 signaling pathway, providing insights for treating inflammatory liver diseases." (PMID 40820881, 2025). "Intestinal endotoxins, such as pathogen-associated molecular patterns, enter the liver through the portal vein system, activate TLR-4 in the liver, and produce inflammatory factors that participate in the development of various liver diseases." (PMID 38666842, 2024). "TLR4 has been studied in multiple diseases, and its role in the pathogenesis of inflammatory liver disease has been demonstrated." (PMID 37676534, 2023). "Now, TNF-α signaling through TLR4 pathway activates multiple intracellular as well as intercellular signaling cascades that lead to progression of liver diseases from steatosis to steatohepatitis, fibrosis and cirrhosis." (PMID 38146363, 2023). "In fact, three studies conducted on TLR4 mutant mice highlighted the key role of TLR4 in the pathogenesis of liver diseases." (PMID 36675276, 2023). "The aim of this review was to explore the multilayer aspects of the TLR4 signaling pathway, regarding its role in liver diseases and HCC, as well as its potential utilization as an immunotherapy target for HCC." (PMID 37345131, 2023).
liver disease (continued). "Some authors have reported that the activation of TLR4 is involved in the development and progression of liver disease." (PMID 37298396, 2023). "Meanwhile, the LPS/TLR4 signaling pathway is primarily responsible for mediating the inflammatory response and pro-fibrogenic activity in numerous liver diseases, and studies have established that this route contributes to liver damage and fibrosis." (PMID 38074148, 2023). "As outlined in the introduction, the TLR4/MyD88-dependent and TLR4/TRIF-dependent pathways are crucial contributors to increased inflammation during LPS-associated liver disease." (PMID 37446388, 2023). "TLR4 signaling has been brought to attention in the past decade regarding its contribution to the development of liver disease." (PMID 37345131, 2023). "LPS is related to the onset and progression of liver diseases and can activate the NFκB pathway via Toll‐like receptor 4 (TLR4) and myeloid differentiation 88 (MyD88)." (PMID 32652882, 2020). "Gut sterilization confined to late stages of hepatocarcinogenesis reduced HCC, suggesting that the intestinal microbiota and TLR-4 represent therapeutic targets for HCC prevention in advanced liver disease." (PMID 31060311, 2019). "MD2, a critical protein in the recognition of LPS by TLR4, has been reported to be vital to the development of liver diseases." (PMID 31861702, 2019). "The functional processes of the gut microbiota–TLR-4 axis in advanced liver diseases, i.e., cirrhosis and HCC, are not well understood, possibly due to complications and obstacles involved in the animal model of ALD." (PMID 31060311, 2019). "And, the possible correlation between Wnt2b and TLR4 in the progression of fibrosis-related liver diseases will be continued in our future work." (PMID 28638086, 2017). "The liver is the main target of intestinally-derived bacterial products and the rate of bacterial translocation increases in various models of hepatic disease, rendering LPS a possible candidate mediator of TLR4-dependent profibrogenic effects." (PMID 25421042, 2015). "Additionally, in patients with chronic viral hepatitis C, TLR4 expression correlates with advanced stages of fibrosis, underscoring its role as a key mediator of inflammation and fibrogenesis in liver disease." (PMID 40332363, 2025). "Gut microbial metabolites such as trimethylamine N-oxide (TMAO), which are elevated in individuals with steatotic liver disease, promote lipid deposition in hepatocytes by increasing intestinal barrier permeability and activating the toll-like receptor 4 (TLR4)/NF-κβ pathway." (PMID 39796579, 2024). "Additionally, TCA can activate hepatic stellate cells by upregulating the Toll-like receptor 4 (TLR4) signaling pathway, thereby playing an important role in both liver remodeling and the development of portal hypertension." (PMID 37759756, 2023). "In addition to the involvement of TLR4 in liver disease, TLR2 signaling contributes to the pathogenesis of liver injury." (PMID 35231062, 2022). "Besides, the TLR4/MyD88/NF-κB signal mainly mediates the inflammatory response, and is a signal transduction pathway regulating liver diseases." (PMID 36311675, 2022). "Serum LPS levels, shown to increase throughout the time course of liver disease, were found to be negatively correlated with Tlr4 (R = − 0.97, P = 0.033) and Myd88 (R = − 0.71, P = 0.041); genes which are well established to be involved in macrophage mediated LPS immunotolerance." (PMID 33858327, 2021). "Therefore, the TLR4/LPS signaling pathway is actively involved in the pathogenesis of liver diseases." (PMID 33207562, 2020). "Ethanol-induced liver disease, a common medical condition, has been reported to be TLR4-dependent; conversely ethanol may potentially compromise antibacterial host defense through effects on TLR activation." (PMID 29481576, 2018). "Therefore, TLR4 signaling in hepatic stellate cell plays important roles in both liver remodeling and portal hypertension development." (PMID 29996772, 2018).